RN7SL454P (RNA, 7SL, cytoplasmic 454, pseudogene)
Gene: Miscellaneous RNA gene on chromosome 17 (78,532,813 to 78,533,055, reverse strand). Ensembl gene ENSG00000243426.
Homologues: Orthologues: chimpanzee Metazoa_SRP (99% identical), pig Metazoa_SRP (74% identical). Paralogues in human: RN7SL4P (78% identical), RN7SL5P (78% identical), RN7SL1 (77% identical), RN7SL2 (77% identical), RN7SL3 (76% identical), RN7SL752P (76% identical), RN7SL357P (75% identical), RN7SL45P (75% identical), RN7SL480P (75% identical), RN7SL277P (75% identical), RN7SL336P (75% identical), RN7SL333P (74% identical), and 703 more.